HNF4A-AS1 (HNF4A antisense RNA 1)
Synonyms: uc002xlx
Gene: Long non-coding RNA gene on chromosome 20 (44,359,756 to 44,395,706, reverse strand). Ensembl gene ENSG00000229005.
Diseases named in the same sentence as HNF4A-AS1 in open-access papers:
HNF4A-AS1 is named in the same sentence as 1 disease in open-access papers, as found by Europe PMC text mining. Sharing a sentence is not in itself a finding about the gene and the disease. The quoted sentences say what the papers report.
neuroblastoma (1 paper, 2022). Neuroblastoma (NB) is the most common solid, extracranial childhood tumor. "Moreover, it was found that high HNF4A-AS1 expression is associated with MYCN amplification in neuroblastoma tumors and that MYCN overexpression or knockdown in neuroblastoma cell lines increases or downregulates HNF4A-AS1 expression, respectively." (PMID 36077650, 2022).